SNORD101 (small nucleolar RNA, C/D box 101)
Synonyms: U101
Gene: Small nucleolar RNA gene on chromosome 6 (132,815,307 to 132,815,379, forward strand). Ensembl gene ENSG00000206754.
Gene Ontology:
Biological process: RNA processing
Cellular component: nucleolus
Homologues: Orthologues: chimpanzee SNORD101 (99% identical), macaque SNORD101 (96% identical), guinea pig SNORD101 (93% identical), pig SNORD101 (89% identical), rabbit SNORD101 (86% identical), mouse Gm23130 (85% identical), rat Snord101 (82% identical).